ITLN1 (intelectin 1)
Diseases named in the same sentence as ITLN1 in open-access papers (continued):
Sharing a sentence is not in itself a finding about the gene and the disease.
gastric cancer (continued). "Mechanistically, ITLN1 attenuated the activity of nuclear factor-kappa B, a transcription factor repressing the HNF4α expression, in gastric cancer cells through inactivating the phosphoinositide 3-kinase/AKT/Ikappa B kinase signaling." (PMID 25965823, 2015). "In summary, for the first time, we have demonstrated that secretory ITLN1 efficiently inhibited the growth, invasion, and metastasis of gastric cancer cells in vitro and in vivo through up-regulating HNF4α in a PI3K/AKT/IKK/NFκB inactivation-dependent manner." (PMID 25965823, 2015). "In the current study, we further demonstrated that secretory ITLN1 suppressed the growth, migration, invasion, and metastasis of gastric cancer cells in vitro and in vivo, suggesting the tumor suppressive roles of ITLN1 in gastric cancer." (PMID 25965823, 2015). "Western blot and real-time quantitative RT-PCR were applied to measure the expression levels of ITLN1 and HNF4α in gastric cancer specimens, normal gastric mucosa, and cultured cell lines AGS, SGC-7901, MKN-28, and MKN-45." (PMID 25965823, 2015). "Matrigel invasion assay showed that gastric cancer cells stably transfected with sh-ITLN1 presented an increased invasion capacity than sh-Scb-transfected cells." (PMID 25965823, 2015). "Our previous studies have shown that ITLN1 is aberrantly expressed in gastric cancer tissues, and is correlated with clinicopathological features, suggesting its value as a useful prognostic factor for gastric cancer patients." (PMID 25889839, 2015). "The ITLN1 levels were significantly lower in gastric cancer cases with poor differentiation (P = 0.019), deeper gastric wall invasion (P < 0.001), lymph node metastasis (P < 0.001), and advanced tumor-node-metastasis (TNM) stage (P = 0.001)." (PMID 25965823, 2015). "ITLN1 is a tumor suppressor in patients with gastric cancer and neuroblastoma." (PMID 33392181, 2020). "Estrogen-Induced Gene 121 Protein (KIAA1324), Long Intergenic Non-Protein Coding RNA 261 (LINC00261), and Intelectin 1 (ITLN1) have been shown to function as tumor suppressors in gastric cancer, with decreased expression associated with poor prognosis." (PMID 31337362, 2019). "Notably, there was a positive correlation between ITLN1 and HNF4α transcript levels in gastric cancer tissues (correlation coefficient R = 0.819, P < 0.001), which was consistent with the results from public datasets." (PMID 25965823, 2015). "This study extends our knowledge about the regulation of tumor suppressive genes associated with the progression of gastric cancer, and suggests that ITLN1 may be of potential values as a novel therapeutic target for gastric cancer." (PMID 25965823, 2015). "Since previous studies indicate that HNF4α affects the growth, invasion, and metastasis of cancers, and combining the evidence that ITLN1 regulated the HNF4α expression, we further investigated the effects of ITLN1 over-expression and target gene restoration on cultured gastric cancer cells." (PMID 25965823, 2015). "Gastric cancer patients with high ITLN1 or HNF4α expression had improved survival probability." (PMID 25965823, 2015). "In clinical gastric cancer tissues, HNF4α expression was positively correlated with that of ITLN1." (PMID 25965823, 2015). "We demonstrated that ITLN1 increased the levels of hepatocyte nuclear factor 4 alpha (HNF4α), resulting in suppression of nuclear translocation and transcriptional activity of β-catenin in gastric cancer cells." (PMID 25965823, 2015). "However, the exact functions, downstream targets, and clinical significance of ITLN1 in gastric cancer still remain elusive." (PMID 25965823, 2015). "In addition, administration of recombinant ITLN1 protein (1 and 2 μg/ml) into cultured gastric cancer cell lines also markedly induced the HNF4α expression at 24 and 36 hrs post-administration." (PMID 25965823, 2015).
gastric cancer (continued). "In addition, restoration of HNF4α expression prevented the gastric cancer cells from ITLN1-mediated changes in these biological features." (PMID 25965823, 2015). "Moreover, restoration of HNF4α expression rescued the gastric cancer cells from ITLN1-mediated suppressive phenotypes, suggesting that ITLN1 may exert its tumor suppressive function, at least in part, through up-regulation of HNF4α in gastric cancer." (PMID 25965823, 2015). "Importantly, western blot and real-time quantitative RT-PCR indicated that ectopic expression or knockdown of NFκB-p65 decreased and increased the expression of HNF4α, respectively, and prevented the gastric cancer cells from ITLN1-mediated changes in HNF4α expression." (PMID 25965823, 2015). "Our data showed that ITLN1 suppressed the activity of NFκB through inactivating PI3K/AKT/IKK pathway, resulting in increased HNF4α expression in gastric cancer cells." (PMID 25965823, 2015). "Our analysis revealed dynamic remodeling of the tumor microenvironment during gastric cancer progression, characterized by the expansion of dysfunctional CD8+ T cells, pro-tumorigenic fibroblasts (e.g., ITGBL1+, PI16+, and ITLN1+), and altered myeloid populations." (PMID 41246350, 2025). "The meta-analysis indicated considerably higher ITLN1 levels in gastrointestinal (i.e., colorectal, pancreatic, gastric) cancer compared to controls, while the other cancer types did not demonstrate differences between groups." (PMID 38482202, 2024). "In addition, the activity of nuclear factor-kappa B (NFκB), a transcription factor repressing the expression of HNF4α, is attenuated by ITLN1 via inactivation of phosphoinositide 3-kinase (PI3K)/AKT/Ikappa B kinase (IKK) signaling, suggesting the tumor suppressive roles of ITLN1 in gastric cancer." (PMID 25965823, 2015).
Insulin resistance (12 papers, 2017 to 2025). Increased resistance towards insulin, that is, diminished effectiveness of insulin in reducing blood glucose levels. "CD295 (rs6700986) and ITLN1 (rs952804) SNPs should be considered as BC-associated susceptibility risk factors in obese, insulin resistance, or pre-diabetic individuals." (PMID 41221514, 2025). "Transcriptome results identified many DEGs linked to insulin resistance, fatty acid β oxidation, and inflammation, including IGF2BP2, LEPR, RAP1A, SESTRIN 3, and ITLN1 that have also been reported in human T2DM." (PMID 40878918, 2025). "Omentin (intelectin-1) was identified at higher plasma concentration in patients with different malignancies, as well as is collated with insulin resistance." (PMID 39941741, 2025). "Omentin-1, also known as intelectin-1 (ITLN-1), is a novel adipocytokine that is involved in a variety of biological events, such as insulin resistance, endothelial dysfunction, programmed cell death and metabolic disorders." (PMID 35141232, 2021). "The plasma ITLN1 level is inversely correlated with BMI, waist circumference and insulin resistance, and it increases with weight loss." (PMID 32669559, 2020). "ITLN1 and CD295 polymorphism testing could be used to assess BC susceptibility in either obese or insulin resistance, pre-diabetic patients." (PMID 41221514, 2025). "In agreement with our observation, MS pigs have the higher homeostasis model assessment-estimated insulin resistance (HOMA-IR) score and triglyceride amount compared to LW pigs, which negatively correlate with ITLN1 plasma concentrations." (PMID 38408058, 2024). "In men with insulin resistance, (after FDR correction only) progranulin levels negatively correlated with ITLN1 SAT expression (ρ = − 0.85, n = 12, adj." (PMID 39333229, 2024).
asthma (11 papers, 2010 to 2024). "In asthma cohort studies in children and adults, we define the genetic and inflammatory regulators of ITLN1 expression, and we show how functional genetic variation in the ITLN1 gene influences susceptibility to airway mucus plugging." (PMID 38724552, 2024). "Notably, a genetic variant at the ITLN1 locus is associated with both Crohn’s disease and asthma, suggesting a role in inflammatory mucosal diseases." (PMID 38724552, 2024). "Notably, using airway mucus plug scores in asthma patients genotyped for the ITLN1 eQTL variant, rs4656959, we discovered that rs4656959 is associated with protection from mucus plugging, specifically among T2-high patients." (PMID 38724552, 2024). "It has been reported that ITLN1 is a biomarker associated with disease susceptibility in asthma." (PMID 35550122, 2022). "Goblet cell gene expression analysis revealed that HDM exposure induced multiple asthma‐associated transcripts, including chloride channel calcium‐activated 1 (Clca1/Gob‐5), mucin 5, subtypes A and C, tracheobronchial/gastric (Muc5ac), intelectin 1 (Itln1), and intelectin 2 (Itln2/B)." (PMID 27621809, 2016). "Furthermore, we demonstrate that both ITLN-1 gene expression and protein levels are significantly reduced by a common genetic variant that is associated with protection from the formation of mucus plugs in T2-high asthma." (PMID 38724552, 2024). "To confirm the airway epithelial cell types expressing ITLN1 in vivo, we performed a single-cell RNA-seq (scRNA-seq) analysis of bronchial airway epithelial brushings from two children with asthma." (PMID 38724552, 2024). "Here, authors reveal a role for intelectin-1 in IL-13-induced mucus properties, and that an ITLN1 eQTL is associated with protection from the formation of mucus plugs in T2-high asthma." (PMID 38724552, 2024). "Here we investigate the molecular role and clinical significance of intelectin-1 (ITLN-1) in the development of pathologic airway mucus in asthma." (PMID 38724552, 2024). "ITLN-1 mRNA expression in freshly isolated BECs was significantly higher in the SN-Asthma group than in the other groups in both distal and proximal airway samples (overall p < 0.0001)." (PMID 28775743, 2017). "In the SN-Asthma group, ITLN-1 mRNA correlated with FeNO, IgE, iNOS, CCL26, periostin and DPP4 mRNA, all Type-2 related parameters." (PMID 28775743, 2017). "In this study, ITLN-1 was induced by IL-13 and mainly expressed in goblet cells of the distal and proximal airways in SN-Asthma patients." (PMID 28775743, 2017). "In this study, we evaluated ITLN-1 mRNA and protein expression in airway cells, tissue and fluid from asthma, COPD, and disease control subjects obtained via bronchoscopy." (PMID 28775743, 2017). "ITLN-1 is induced by IL-13 and expressed mainly in goblet cells in untreated asthma where its levels correlate with known Type-2 related parameters." (PMID 28775743, 2017). "It was also reported that intelectin-1 was related to chronic obstructive pulmonary disease and asthma." (PMID 20628387, 2010). "In conclusion, our results suggest that ITLN-1 contributes to T2 inflammation-induced airway mucostasis and airway plugging and that a common ITLN1 eQTL variant mediates the risk of poor mucus-related outcomes in patients with severe T2-high asthma." (PMID 38724552, 2024). "The hub gene ITLN1, which is expressed in airway epithelial cells and involved in inflammatory pathways downstream of IL-13, was found to be significantly upregulated in the bronchial brushings of patients with asthma compared with controls." (PMID 35550122, 2022). "Thus, further studies are needed to better understand the interactions between ITLN-1 and lactoferrin in asthma." (PMID 28775743, 2017). "The ratio of ITLN-1/albumin was significantly higher in SN-Asthma." (PMID 28775743, 2017). "In contrast, ITLN-1 was easily detected in serum in ST and SN-Asthma cases." (PMID 28775743, 2017).
asthma (continued). "In this study, ITLN-1 mRNA significantly correlated with FeNO and serum IgE, as well as iNOS, CCL26, periostin and DPP4 mRNA in SN-Asthma, as these genes are known to be induced in BECs stimulated with IL-13." (PMID 28775743, 2017). "ITLN-1 was detected in BAL and higher in SN-Asthma than ST-Asthma cases, although the concentrations were very low." (PMID 28775743, 2017). "However, no reports have compared ITLN-1 with other asthma biomarkers or revealed its function in human asthma." (PMID 28775743, 2017). "However, it appears to be suppressed by corticosteroids in vivo, and epithelial ITLN-1 does not appear to contribute substantially to serum levels, making it unsuitable as a Type-2 asthma biomarker." (PMID 28775743, 2017). "There were no any differences in serum ITLN-1 concentration between ST and SN-Asthma." (PMID 28775743, 2017). "Thus, it does not appear that serum ITLN-1 will be a valid asthma biomarker." (PMID 28775743, 2017). "ITLN-1 was abundant in serum (range 77.3–385 ng/mL); but serum ITLN-1 was indistinguishable between ST-Asthma and SN-Asthma patients." (PMID 28775743, 2017). "ITLN-1 mRNA expression and protein were measured with or without IL-13 stimulation (10 ng/mL) in primary human BEC derived from both ST and SN-Asthma cultured in ALI." (PMID 28775743, 2017).
ovarian carcinoma (10 papers, 2020 to 2025). A malignant neoplasm originating from the surface ovarian epithelium. "Ovarian cancer (OC) cells have been observed to modify mesothelial cells in visceral adipose tissue by downregulating ITLN1, thereby enhancing the invasion potential and proliferation of OC cells in the omental microenvironment." (PMID 38612764, 2024). "Here, the authors show that circulating intelectin-1 (ITLN1) has prognostic significance in patients with advanced ovarian cancer, and that mesothelial cell-derived ITLN1 in the omental tumor microenvironment suppresses ovarian cancer progression." (PMID 32669559, 2020). "Further studies demonstrate that ITLN1 suppresses lactotransferrin’s effect on ovarian cancer cell invasion potential and proliferation by decreasing MMP1 expression and inducing a metabolic shift in metastatic ovarian cancer cells." (PMID 32669559, 2020). "Here, we show that circulating ITLN1 has prognostic significance in patients with advanced ovarian cancer." (PMID 32669559, 2020). "ITLN1 has been reported to inhibit metastasis in neuroblastoma, gastric tumor, and ovarian cancer." (PMID 41218553, 2025). "Moreover, these authors observed that ITLN1 mRNA was expressed at a lower level in the omental adipose tissue of patients with high-grade ovarian cancer compared with women with benign disease." (PMID 35186726, 2022). "Additionally, ovarian cancer-bearing mice treated with ITLN1 demonstrate marked decrease in tumor growth rates." (PMID 32669559, 2020). "ITLN1, conversely, antagonizes tumor neovascularization and MDSC accumulation via IL-17D/CXCL2 axis modulation, thereby reshaping the immunosuppressive TME—a mechanism aligning with its prognostic significance in both CRC and ovarian cancer." (PMID 40145096, 2025). "Another study evaluating the same topic indicated that circulating ITLN1 was lower in patients with high-grade ovarian cancer as opposed to healthy women and women with benign gynecological disease." (PMID 35186726, 2022).
colorectal cancer (8 papers, 2015 to 2025). A primary or metastatic malignant neoplasm that affects the colon or rectum. "The impact of ITLN1 on the prognosis of colorectal cancer and its underlying mechanisms are worthy of further exploration in the future." (PMID 39399504, 2024). "Another study evaluating a cohort of Chinese patients identified increased ITLN1 levels as a potential risk factor for colorectal cancer." (PMID 35186726, 2022). "Quantitative proteomic techniques have also revealed the value of ITLN1 as a useful proteomic tool for risk stratification and prediction of poor outcome in colorectal cancer." (PMID 25889839, 2015). "A review by the same authors consolidated emerging evidence that omentin-1 (intelectin-1) may function as a tumor-suppressive adipokine in colorectal cancer, with its local bioavailability tightly linked to the processing chaperone TMEM207." (PMID 41149627, 2025). "Moreover, our identification of ITLN1+ fibroblasts as a metastasis-associated population extends recent findings linking ITLN1 to matrix remodeling and tumor dissemination in colorectal cancers." (PMID 41246350, 2025). "Similarly, higher tumor expression of ITLN1 was associated with improved prognosis in patients with colorectal cancer." (PMID 35186726, 2022). "In colorectal cancer, elevated circulating omentin-1 has shown diagnostic accuracy comparable to conventional tumor markers, while intratumoral ITLN1 expression and its stabilization by TMEM207 may serve as independent prognostic indicators and therapeutic modulators." (PMID 41149627, 2025). "Higher levels of circulating ITLN1 were also found to increase the probability of recurrence or death in colorectal cancer after surgery; yet, the difference in circulating ITLN1 between the groups was very small." (PMID 35186726, 2022). "A study by Ummugul Uyeturk and colleagues examined circulating ITLN1 levels after surgery and chemotherapy in colorectal cancer and found that the levels remained elevated compared with a healthy control group who did not have surgery or chemotherapy." (PMID 35186726, 2022). "In colorectal cancer cell lines, the reduction of ITLN1 expression by short-hairpin RNA increased cell growth and proliferation as well as Akt, extracellular signal-regulated kinase (ERK), and epidermal growth factor receptor (EGFR) phosphorylation." (PMID 35186726, 2022). "A recent systematic review examining circulating ITLN1 levels in cancer found that ITLN1 was often increased in individuals with colorectal cancer compared with healthy controls." (PMID 35186726, 2022). "The siRNA-mediated downregulation of TMEM207 resulted in polyubiquitination followed by proteasome degradation of intelectin-1 and decreased intelectin-1 secretion by colorectal cancer cells." (PMID 28422056, 2017). "A case–control study in 358 patients with colorectal cancer (CRC) and 286 age- and BMI-matched controls examined the functional missense variant rs2274907 A > T (Val109Asp) in the ITLN1 gene to assess its contribution to cancer susceptibility and adipokine regulation." (PMID 41149627, 2025). "In comparison, two studies have found that higher tumor expression (rather than circulating levels) of ITLN1 was associated with a good prognosis in colorectal cancer." (PMID 35186726, 2022). "An un-identified surface membrane protein may act as a receptor of intelectin-1 in colorectal cancer." (PMID 28422056, 2017). "Here, we discuss the recent understanding of the role of adipokines in colorectal carcinogenesis and subsequently describe the potent tumor suppressor roles of intelectin-1 and TMEM207 in colorectal cancer." (PMID 28422056, 2017).